HIF1A (hypoxia inducible factor 1 subunit alpha)
Diseases named in the same sentence as HIF1A in open-access papers (continued):
Sharing a sentence is not in itself a finding about the gene and the disease.
breast cancer (continued). "We also compare these results with a gene-expression analysis from a compendium of four human breast cancer datasets, and show a clear association between high LDH-A and HIF-1α expression and poor clinical outcome (metastases-free survival)." (PMID 30248111, 2018). "Kim and Colleagues indeed showed that selective deletion of HIF-1a (or VEGFA) in fibroblast was enhancing tumour growth in murine mammary cancer models." (PMID 29362402, 2018). "This has been further confirmed using conditional knock out mice, where it was demonstrated that HIF-1α was necessary for both primary mammary tumor growth and metastasis to lymph nodes and lungs." (PMID 29628507, 2018). "A previous study showed that increased expression level of HIF-1α usually predicts poor treatment outcomes of chemoendocrine therapy and low disease-free survival rate in patients with primary breast cancer." (PMID 29899167, 2018). "Both of these MDR are regulated by hypoxia and HIF-1α expression is crucial for chemotherapy resistance in breast cancer stem cells." (PMID 30555629, 2018). "We also found that silence of P4HA1 reduced ECAR in breast cancer cells, and HIF-1α PPAA mutant restored ECAR in P4HA1-silenced cells." (PMID 30367042, 2018). "Nevertheless, the fact that P4HA1 expression correlates with HIF-1 activation in breast cancer tissues suggests that hyperactivation of HIF-1α in TNBC is at least partially induced by P4HA1." (PMID 30367042, 2018). "Elevation of ROS levels is crucial also for the copper-dependent induction of HIF-1α expression in breast cancer cells." (PMID 29996493, 2018). "A careful analysis of western blot images unveils that the expression of HIF-1α is significantly increased in the hereditary breast cancer cells, suggesting a specific role of BRCA1 in regulating this factor." (PMID 29584711, 2018). "Further extending the cooperation between GPER and HIF-1α in tumor progression and invasion, we reported that in normoxic breast cancer cells estrogen-activated GPER induces HIF-1α expression and its target gene VEGF." (PMID 29996493, 2018). "In the present study, we demonstrated that IDH1 depletion in breast cancer cells led to an increase in the HIF1α protein level to promote cell migration and invasion." (PMID 29661250, 2018). "Treatment with dimethyl-succinate slightly increased HIF-1α protein levels in P4HA1-silenced breast cancer cells." (PMID 30367042, 2018). "In a compendium of four human breast cancer datasets, we show a clear association between high LDH-A and HIF-1α gene expression and poor outcome, and an inverse pattern of disease-free survival with immune-related gene expression (CD3E/CD4 and CD8A)." (PMID 30248111, 2018). "LINK-A recruits breast tumor kinase (BRK) to phosphorylate Tyr565 of hypoxia-inducible factorα (HIF1α), and the activated HIF1α signaling promotes breast cancer glycolysis reprogramming." (PMID 29458374, 2018). "On the other hand, a tumor-suppressive role for the HIF-1α/GPER signaling was demonstrated in certain sub-populations of breast cancer recapitulating the molecular features of the triple negative subtype." (PMID 29996493, 2018). "Recently, the chemotherapeutic agents, paclitaxel or gemcitabine, were shown to induce HIF-1α transcriptional activation through elevation of ROS levels and in turn promote the chemo-resistance of breast cancer stem cells." (PMID 29996493, 2018). "Extending the framework of these findings, estrogens were reported to regulate HIF-1α activity both in normoxic and hypoxic conditions in breast cancer." (PMID 29996493, 2018). "SWI/SNF-related matrix-associated actin-dependent regulator of chromatin subfamily E member 1 (SMARCE1) is known to play an essential role in breast cancer metastasis by protecting cells against anoikis through the HIF1A/PTK2 pathway." (PMID 29728663, 2018).
breast cancer (continued). "Despite the stimulatory role mediated by E2/ERα signaling on HIF-1α expression in breast cancer, the interaction between estrogen signaling and HIF-2α shows an opposite trend." (PMID 29996493, 2018). "One pathway in breast cancer that occurs downstream of hypoxia and HIF-1α involves transforming growth factor (TGF)-β signalling." (PMID 29098360, 2018). "For example, it has been reported that the metastatic potential of breast cancer is increased in patients undergoing anti-angiogenic therapy, possibly because of positive modulation of HIF-1α activity under hypoxic conditions." (PMID 30013951, 2018). "In several of the cell types, Notch activation also led to decreased HIF1α protein levels: this was observed in D324 cells and primary breast cancer both at normoxia and hypoxia, as well as in the MDA-MB-231 cells after 72 h in hypoxia." (PMID 29993038, 2018). "In this report we find that many genes regulated by the ERβ variants are direct targets of either HIF-1α or HIF-2α indicating a potentiation of hypoxic signaling, which has previously been shown to affect breast cancer aggressiveness." (PMID 29552303, 2018). "The differential activation of the HIF-1 pathway in breast cancer subtypes suggests that oxygen-independent pathways are involved in HIF-1α regulation during TNBC progression." (PMID 30367042, 2018). "In contrast, HIF-1α expression was sharply reduced in transfected IL-6 siRNA or Dia exposed breast cancer cells in hypoxic environment." (PMID 29695771, 2018). "In the second part of this review, we describe the role of hypoxia signaling in breast cancer cells and discuss recent evidence regarding a functional interaction between HIF-1α and GPER in both breast cancer cells and cancer-associated fibroblasts (CAFs)." (PMID 29996493, 2018). "In a mammary carcinoma model, HIF-1α increased immediately after 1 hour of hyperthermia treatment and was restored 48 hours later." (PMID 30420794, 2018). "The distribution of HIF-1α was decreased by 35% in breast cancer cells and the expression of VEGFs was reduced as well." (PMID 28993797, 2017). "Low Parkin expression was significantly correlated with high HIF-1α levels in these three cohorts of breast cancer." (PMID 29180628, 2017). "In a further one, in human breast cancer cells, cancer-associated oxidoreductase ERO1-α over-expression increased HIF-1α protein expression." (PMID 29099748, 2017). "Here the authors show that Parkin regulates HIF-1α through ubiquitin-dependent degradation, thus inhibiting metastasis of breast cancer cells." (PMID 29180628, 2017). "XBP1 is activated in TNBC and has a pivotal role in the tumorigenicity and progression of this human breast cancer subtype by controlling HIF1α pathway." (PMID 28245581, 2017). "HIF1α plays a key role in many crucial aspects of breast cancer biology, including stem cell maintenance, metabolic reprogramming, EMT, metastasis, and resistance to therapy." (PMID 28061479, 2017). "To this end, we first immunohistochemically labeled 24 breast cancer and uninvolved adjacent normal tissue samples (samples obtained by partial mastectomy pretreatment) for HIF-1α and calculated weighted indices (WIs) for nuclear HIF-1α." (PMID 28272508, 2017). "All of this is supported by the findings of co-expression of HIF-1α and the CD44+/CD24−/low phenotype (self-renewal ability) associated with worse prognosis of breast cancer patients." (PMID 29099748, 2017). "Module 2 includes genes whose abnormal function has been directly associated with breast cancer, such as MAPK14, BRCA1, CDH1, HIF1A, CDKN2A and other members/regulators of the CDK family." (PMID 29093438, 2017). "Based on several studies, it is thought that UCA1 either manipulates the mTOR signaling pathway and/or exploits an miR-18a-HIF1α feedback loop as well as the Wnt/β-catenin signaling pathway to confer tamoxifen resistance in breast cancer." (PMID 29299178, 2017).
breast cancer (continued). "The expression of hypoxia markers in breast cancers, such as HIF-1α and CA9, correlates with a more aggressive disease type and poor prognosis." (PMID 28642487, 2017). "This supports that breast cancer cells also undergo different phases of hypoxic induction with substantive differences over time that are consistent with differential HIF1α/HIF2α activities." (PMID 28642487, 2017). "Here we find that modulation of Hif1-α expression plays a role in claudin-low breast cancer adaptation to exercise." (PMID 29254140, 2017). "Considering the role of Parkin in downregulation of HIF-1α, our results suggest that the frequent Parkin downregulation in breast cancer contributes to HIF-1α overexpression in cancer." (PMID 29180628, 2017). "Previous studies in breast cancer cells showed that estradiol induces the expression of HIF1A, which is involved in the transcriptional regulation of VEGF." (PMID 29137421, 2017). "In summary, our results demonstrate that Parkin is an important E3 ubiquitin ligase for HIF-1α, which inhibits breast cancer metastasis through ubiquitination and degradation of HIF-1α." (PMID 29180628, 2017). "Previous studies suggested that HIF-1α- or TGFβ1-induced miR-382-5p expression led to the inhibition of the ERβ-RERG tumor suppressive signaling cascade in breast cancer." (PMID 27705918, 2017). "Specifically, the HIF-1α-dependent induction of lysyl hydroxylase activity is required for breast cancer and sarcoma cell migration." (PMID 28507454, 2017). "Parkin downregulation in breast cancer cells promotes metastasis, which can be inhibited by targeting HIF-1α with RNA interference or the small-molecule inhibitor YC-1." (PMID 29180628, 2017). "Collectively, these results indicate that Parkin inhibits migration and invasion of breast cancer cells, and the negative regulation of HIF-1α contributes to this function of Parkin." (PMID 29180628, 2017). "For comparison, we also assessed the HIF1A mRNA expression of breast cancer cells cultured for 1 week in low-density collagen under 21% oxygen, in high-density collagen under 1% oxygen, and in high-density collagen under 21% oxygen." (PMID 29162797, 2017). "This conclusion is consistent with reports that HIF-1α is critical for the metastatic progression of breast cancer while HIF-2α is expressed in a tissue restricted fashion that does not include the mammary gland." (PMID 28320353, 2017). "Taken together, these findings indicate that HIF-1α reduces ER-α levels in response to hypoxia in breast cancer." (PMID 28320353, 2017). "Parkin interacts with HIF-1α and promotes HIF-1α degradation through ubiquitination, which in turn inhibits metastasis of breast cancer cells." (PMID 29180628, 2017). "JMJD2C/KDM4C interacts with HIF1A to enhance target gene activation and promote breast cancer progression and metastasis by demethylating H3 lysine 9 near several HIF1A target genes." (PMID 27756687, 2017). "GPER has previously been reported as a target of HIF1-α in breast cancer cells and here we confirm that hypoxia induces the expression of GPER in CRC cells." (PMID 29137421, 2017). "HIF-1α is a major determinant of invasion and metastasis in a wide variety of tumor types including breast cancer." (PMID 29100336, 2017). "Our results in this study demonstrate that Parkin inhibits migration, invasion and metastasis of breast cancer cells through its ubiquitination and degradation of HIF-1α." (PMID 29180628, 2017). "E-cadherin knockdown in human breast cancer cell line xenografts has been shown to decrease tumor growth due to impaired HIF-1α expression and subsequent ability to metabolize glycogen as an energy source." (PMID 28750639, 2017). "We show marked differential sensitivity of breast cancer to exercise treatment, which occurred with parallel changes to Hif1-α protein, and metabolism." (PMID 29254140, 2017).
breast cancer (continued). "Selective inhibition of HIF-1α expression in mammary epithelium leads to lactation failure and in breast cancer models to increased tumor growth." (PMID 28993797, 2017). "Hypoxia causes cells to overexpress hypoxia-inducible factor 1 alpha (HIF1α) and vascular endothelial cell growth factor (VEGF) which is associated with unfavorable prognosis in breast cancer patients." (PMID 28693495, 2017). "When breast cancer cells are exposed to tamoxifen, the expression of HIF1-α increases, which stimulates over-expression of UCA1, and thereby enhances β-catenin translocation into the nucleus, promoting the extracellular redistribution of the ER." (PMID 29299178, 2017). "In contrast, activation of HER2 receptor in breast cancer cells increases HIF-1α synthesis via stimulation of HIF-1α mRNA translation in a rapamycin-sensitive manner." (PMID 29104248, 2017). "Controversially to this suggestion, it was published that FOXO3 is activated downstream of HIF-1α in fibroblasts as well as in breast cancer cells." (PMID 29250065, 2017). "In breast cancer, hypoxia inducible factor (HIF1α) induction can enrich the breast cancer stem cell population via interleukin 6 (IL6) and IL8 activation of ABCB1." (PMID 29117122, 2017). "For instance, high levels of HIF-1α correlate with poor clinical outcomes in human breast cancer, with HIF-1α being the master regulator of Epithelial-Mesenchymal Transition (EMT), invasion, extravasation, and metastasis in this type of tumor." (PMID 28536364, 2017). "Hypoxia and estrogen are functionally equivalent in breast cancer cells and E2 induces an increase in both HIF1A and VEGF gene expression." (PMID 29137421, 2017). "Whereas knockdown of HIF-1α reduced migration and invasion of various breast cancer and MCF10A cells, knockdown of Parkin had a significantly less pronounced promoting effect on migration and invasion in cells with HIF-1α knockdown." (PMID 29180628, 2017). "Conversely, treatment of breast cancer cell lines and a mouse xenograft model with docetaxel, a potential breast cancer drug, causes cell death in hypoxic conditions through c-Jun N-terminal Kinase 2 (JNK2)-PHD1 mediated HIF-1α degradation." (PMID 28536364, 2017). "In primary breast carcinoma with low or null Wwox, HIF-1α levels are controlled through stabilization dependent on hypoxia and oncogenes." (PMID 28045433, 2017). "Further, we observed higher levels of HIF-1α expression in OID mammary tumors compared with control tumors (p = 0.03)." (PMID 27339599, 2016). "The participation of mTOR in the regulation of HIF-1α protein translation was first shown in a study with breast cancer cells where stimulation with heregulin and HER2 signaling increased the rate of HIF-1α synthesis in a rapamycin-dependent manner." (PMID 26942179, 2016). "The survival of patients with breast cancer whose plasma level of HIF-1α was lower than median was much greater than the survival of patients whose plasma level of HIF-1α was higher than the median (P=0.001)." (PMID 27780920, 2016). "Endogenous STAT3 and HIF-1α expression in breast cancer cells with miR-106a/b transfection were examined." (PMID 27325313, 2016). "Elevated HIF-1α induced miR-424 decreased breast cancer sensitivity to doxorubicin by suppressing the expression of PDCD4, known as an apoptosis-related protein, and subsequently inhibiting the expression of caspase-3 and PARP." (PMID 27016414, 2016). "Downregulation of HIF-1α expression by shRNA inhibited proliferation, migration, and invasion of cancer cells in vitro, and decreased tumor growth in breast cancer xenograft models." (PMID 27557521, 2016). "Our results illustrated that EMMPRIN has an important role in breast cancer stem-like cells by activation STAT3/HIF-1α through interaction with cancer cells and fibroblasts." (PMID 27325313, 2016). "Overexpression of HIF-1α was found to predict early relapse in breast cancer in a retrospective study with 745 patients." (PMID 27187355, 2016).
breast cancer (continued). "Increased EMMPRIN expression in activated fibroblasts increased the expression of STAT3 and HIF-1α and showed cancer stem-like cell features in breast cancer cells." (PMID 27325313, 2016). "Here, we aimed to explore HIF-1α expression in a series of African breast cancers in relation to Axl expression and other tumor characteristics." (PMID 26760782, 2016). "Hypoxia induces RANK and RANKL mRNA and protein in MDA-MB-231 and MCF-7 breast cancer cells in a HIF-1α dependent manner, and has also been shown to accelerate RANKL-mediated cell migration." (PMID 27706047, 2016). "CD44 expression has been reported higher in breast cancer stem cells under conditions of hypoxia than normoxia, and HIF-1α was found to control CD44 expression in these cells." (PMID 27347945, 2016). "Here, we aimed to evaluate HIF-1α in relation to Axl expression, angiogenesis markers, and other tumor characteristics in a series of African breast cancer." (PMID 26760782, 2016). "Recent research further shows that XBP1 is a coregulator of HIF1α and controls the HIF1α transcriptional program in breast cancer." (PMID 27133203, 2016). "We notified that UA increases VHL mRNA expression in breast cancer cells, which leads a low level of HIF-1α and HIF-2α." (PMID 27708244, 2016). "Inhibiting HIF1α in combination with anti-angiogenic therapy reduces CSCs in mouse models of breast cancer and holds promise to be an effective therapy in breast cancer, which is currently being investigated in clinical trials." (PMID 27220421, 2016). "Our study provides evidence suggesting an essential role of SMARCE1-based chromatin remodeling activity in breast cancer metastasis by facilitating HIF1A-mediated PTK2 transcription activation in detached cells under normoxia." (PMID 27495308, 2016). "In this report, we show that HIF-1α-overexpressing breast cancer cells, MDA-MB-231, secrete heat shock protein-90alpha (Hsp90α) and use it to survive under hypoxia." (PMID 26846992, 2016). "Despite controversial and partially divergent reports, HIF-1α seems to promote primary mammary tumor growth and metastasis." (PMID 27780920, 2016). "Further studies revealed the presence of a cross-talk between estrogen signaling pathways and HIF-1α regulation in breast cancer." (PMID 27105516, 2016). "We previously demonstrated that treatment of breast cancer cells with digoxin inhibits the hypoxic induction of HIF-1α protein and HIF target gene expression." (PMID 27590511, 2016). "Tumor cell invasion is the first step for tumor metastasis, so we tested the anti-invasion effects of UA and CAY10585 (HIF-1α inhibitor) on a highly invasive breast cancer cells MDA-MB-231." (PMID 27708244, 2016). "Here, we report a strong co-expression of HIF-1α and Axl in this breast cancer cohort, supporting previous findings that Axl expression is increased within hypoxic tumor areas." (PMID 26760782, 2016). "Enrichment for CD49f in breast cancer cells also enriches for HIF-1α expression and expression of downstream HIF target genes." (PMID 27001172, 2016). "Under normoxic culture conditions, we found almost four times more HIF-1α protein levels in the DTC-tumor cell line compared to the mammary tumor cell line, in which HIF-1α was barely detectable." (PMID 27105499, 2016). "Another interesting observation of our study is that cells derived from DTC tumors maintain high basal levels of HIF-1α protein compared to the mammary tumor cell line." (PMID 27105499, 2016). "After short in vitro expansion (2 to 4 passages) of the cells derived from a DTC tumor (DTC tumor cell line) and mammary tumor (Mammary tumor cell line) we evaluated protein levels of HIF-1α by Western blotting." (PMID 27105499, 2016). "The common chemotherapy drugs paclitaxel, gemcitabine and carboplatin have been recently shown to induce HIF-1α expression in various models of breast cancer in a reactive oxygen species dependent manner." (PMID 27066484, 2016).